NLRP3 (NLR family pyrin domain containing 3)
Diseases named in the same sentence as NLRP3 in open-access papers (continued):
Sharing a sentence is not in itself a finding about the gene and the disease.
tumor (continued). "NOD-like receptor family pyrin domain containing 3 (NLRP3) inflammasome activation within the tumor microenvironment can induce the activation of IL-1β, which subsequently activates RORγt to promote the secretion of IL-22 by Th17 cells, thereby promoting disease advancement." (PMID 37680632, 2023). "Knockout of Nlrp3 and Caspase1 inhibited the tumor growth in mice with 5-FU." (PMID 36457716, 2022). "The polarization of TAMs toward M1 by HPP in the tumor microenvironment may be mediated by the NF-κB/NLRP3 pathway." (PMID 35603205, 2022). "Altogether, these studies highlight the tumor suppressive role of the NLRP3 inflammasome." (PMID 35740272, 2022). "However, the expression of STAT3-target genes Il11 and Socs3 was similar among gp130F/F:Nlrp3-/- and gp130F/F tumor and matched non-tumor gastric tissues at 3 and 6 months of age." (PMID 35299732, 2022). "Knockdown of NLRP3 can inhibit MDSCs and effectively control malignant tumour proliferation." (PMID 35435776, 2022). "Gene expression analyses by qPCR also indicated that NLRP3 deficiency did not significantly alter the mRNA levels of other inflammasome-associated PRRs in tumor samples from gp130F/F mice." (PMID 35299732, 2022). "Similarly, analysis of NLRP3 expression in 83 patients for which there were paired tumor and adjacent non-tumor tissues indicated that NLRP3 was significantly upregulated in tumors from 82% (68/83) of patients." (PMID 35299732, 2022). "Flow cytometry analysis demonstrated robust expression of NLRP3 and pro-IL-1β in MDSCs from spleens of naïve mice as well as in highly pure MDSCs isolated from tumor-bearing mice, and this is accompanied by increased levels of secreted IL-1β as determined in culture supernatants." (PMID 36032139, 2022). "After the NLRP3 inflammasome is activated, it causes an inflammatory cascade reaction, leading to the release of pro-inflammatory factors such as IL-1β, IL-18, IL-22, TNF-α, and the activation of inflammation-tumor signaling pathways such as NF-κB." (PMID 35292015, 2022). "This antibody alone attenuates tumor growth, and when combined with the PD-1 antibody, it further slows tumor progression; 50% of mice show complete tumor rejection via a mechanism associated with P2RX7/NLRP3/IL-18 activation in myeloid cells." (PMID 35454832, 2022). "In addition, in previous studies, benzimidazole was found to trigger GBM pyroptosis via the NF‐κB/NLRP3/GSDMD pathway to achieve anti‐tumour effects." (PMID 35083859, 2022). "Indeed, myeloid- or CAF-specific deletion of genes involved in Nlrp3 inflammasome activation leads to decreased tumor growth." (PMID 35517498, 2022). "NLRP1/NLRP3 expression was varied among datasets for the same tumor type." (PMID 36541912, 2022). "However, when the tumor metastasizes, NLRP3 expression is significantly reduced and promotes tumor development." (PMID 36233009, 2022). "This phenomenon depends on tumor cells activating the NLRP3 inflammasome to produce IL-1β." (PMID 36248807, 2022). "Previous studies have revealed the finding that NLRP3 is overexpressed in CRC tumor tissues." (PMID 35890097, 2022). "Consequently, we analyzed NLRP1/NLRP3 expression in different tumor types based on TCGA RNA-seq data." (PMID 36541912, 2022). "Finally, therapeutic targeting of NLRP3 inhibited tumor development and re-programmed the MDSC compartment." (PMID 36032139, 2022). "However, corylin inhibited the mRNA expression and protein levels of Ifnγ, Tnf-α, Il-6, Il-1β, Nlrp3, Asc, Pannexin, and Pro-caspase 1 in the tumor tissues of AOM/DSS-induced CAC mice." (PMID 35269806, 2022). "The effects of SCFA, an inhibitor of histone deacetylase, have been shown in Caco-2 tumor cells that have been stimulated with LPS to suppress expression of all NLRP3 components, attenuate intestinal barrier dysfunction, inhibit ROS generation, and activate autophagy." (PMID 36082127, 2022).
tumor (continued). "Recent research has shown that mutations in single genes, such as POLE, NLRP3, COL3A1, and PTPRT could predict tumor TMB and immunotherapeutic response." (PMID 35884556, 2022). "P2X7R promoted tumor growth in several solid tumors by activating the NLRP3 inflammasome." (PMID 35739593, 2022). "NLRP3 signalling in macrophages drives the change of the adaptive immune response to be tolerogenic as it promotes the differentiation of existing T-cells into tumour-promoting T-cells." (PMID 35877745, 2022). "Helicobacter pylori, Epstein Barr virus and HPV can induce high expression of NLRP3 in tumour cells; promote malignant proliferation, distant metastasis, resistance to apoptosis and angiogenesis; and significantly reduce the efficacy of chemotherapy in patients." (PMID 35435776, 2022). "Additionally, the activation of NLRP3 can reshape the tumour immune microenvironment, recruit MDSCs, weaken the body's antitumour immunity, assist tumour cells in resisting chemotherapy, and reduce the sensitivity of tumour cells to oxaliplatin." (PMID 35435776, 2022). "Besides TAMs, PDAC tumor cells also activate the Nlrp3 inflammasome and act as a prominent source of IL-1β." (PMID 35517498, 2022). "Furthermore, NLRP3 inflammasome blockade can delay tumour-burdened speed in transgenic head and neck SCC mice." (PMID 36325196, 2022). "Over the past few years, the role of NLRP3 in different tumor types has gained interest." (PMID 35745570, 2022). "Furthermore, several anti-tumor agents were shown to induce IL-1β mostly in a NLRP3 inflammasome–dependent manner; therefore, the treatment of tumors with the combination of conventional agents and anti-IL-1β has been adapted." (PMID 35739593, 2022). "Subsequently we showed that NLRP3-mediated IL-1β production drives tumor growth in vivo." (PMID 36439171, 2022). "Gene sets of tumor immune-related enriched in NLRP1/NLRP3 high expression Group." (PMID 36541912, 2022). "Moreover, NLRP3 mediates pyroptosis by triggering caspase 8 activation, indicating its roles in regulating tumor cell death and tumor–immune interaction." (PMID 36497253, 2022). "NLRP3 belongs to the NLR family of pattern recognition receptors, which are important in innate immunity, including the modulation of the polarization of tumor-associated macrophages to M1." (PMID 36497253, 2022). "Furthermore, a fourth study revealed that activation of the NLRP3 inflammasome was increased in tumour specimens from patients who had received fluorouracil chemotherapy and oral SCC cells after fluorouracil treatment." (PMID 36325196, 2022). "The role of NLRP3 in the tumour microenvironment is elusive." (PMID 35877745, 2022). "Another study in head and neck squamous cell cancer indicated that IL-1β could be activated by NLRP3 that is related to the anti-tumor immune responses and tumor progression." (PMID 36276158, 2022). "ssGSEA analysis also associated both these macrophage subsets with alterations in several pathways related to carcinoma progression, T cell exhaustion, cell migration, sprouting angiogenesis, and wound healing, in agreement with tumor supportive roles reported for NLRP3 and INHBA." (PMID 36439171, 2022). "The activation of NLRP3 inflammasome was related to the tumor pathogenesis." (PMID 35144617, 2022). "In addition, luteolin treatment (50 mg/kg/day i.p. injected) increased ASC, cleaved caspase-1, IL-1β, and NLRP3 protein levels in xenografts of HT-29 cells in nude mice, simultaneously decreasing tumor size." (PMID 36555392, 2022). "As NLRP3 activation and IL-1β secretion could promote tumor growth and contribute to chemotherapy resistance, considerations should be made before using lactamides." (PMID 36012769, 2022). "The vast majority the NLRP3 activations lead to tumor growth regression, with a few exceptions." (PMID 35804922, 2022). "In support of this hypothesis chemotherapy-induced cathepsin B release demonstrated to activate NLRP3 inflammasome in MDSCs, curtailing anti-tumor immunity." (PMID 36032139, 2022).
tumor (continued). "Within the tumour microenvironment (TME), the enrichment of eATP released from stressed or dying tumour cells could stimulate cell inflammation activity, including NLRP3 inflammasome activation, thus triggering the activation of T cells." (PMID 35999267, 2022). "The controversy maybe due to NLRP3’s broad activity in intrinsic properties and microenvironments of a tumor cell, and further studies are needed to explain the diversity of its functions." (PMID 36619871, 2022). "In addition, CRGs correlated with the level of immune cell infiltration, TMB, MSI, and tumor stemness score, with NLRP3 being more strongly correlated." (PMID 36387247, 2022). "We further studied the relative expression of core cuprotosis risk genes NFE2L2, NLRP3, SLC31A1, and GCSH in GC STAD and confirmed that NFE2L2 has low expression in STAD tumor tissue, while SLC31A1 and GCSH genes were highly expressed in STAD tumor tissue." (PMID 36249422, 2022). "In many cases, the inflammatory TME contributes to metastasis by recruiting blood and lymph vessels, such as the S1PR1 on tumor-associated macrophages (TAMs), which triggers lymphangiogenesis, tumor angiogenesis, and metastatic spread via NLRP3/IL-1β in pulmonary cancer." (PMID 35892884, 2022). "Additionally, it is important to note that there was reduced NLRP3/caspase-1 complex activity in the transgenic tumor-bearing mice upon treatment with anti-CTLA4 in all three cohorts." (PMID 35741331, 2022). "Importantly, the impact of activation of NLRP3 in cancer cells versus the host cells during tumor immune surveillance remain ill defined." (PMID 36032139, 2022). "Among the somatic mutations detected in the tumor samples, two alternations were found in the coding region of NLRP3, including one synonymous mutation (c.1299C>A) and one nonsynonymous mutation (c.1300 C>A)." (PMID 36091765, 2022). "Since MSU is known to serve as a potent activator of the NLRP3 inflammasome, facilitating the synthesis of IL-1β and other inflammatory mediators, we assumed that inflammasome activation in the tumor environment controls the trafficking of excessively aging neutrophils to malignant tumors." (PMID 34876407, 2021). "We first asked whether LNCaP and PC3 cell lines, characterized by different androgen responsiveness and thus modelling different tumor progression stages, may have a different inflammatory profile regarding NLRP3-inflammasome activation and IL-1β maturation." (PMID 34070682, 2021). "Genetic alterations that influence the activity of the NLRP3 signaling axis are likely to impact T cell-mediated tumor cell killing and may indicate which tumors rely on this pathway for immune escape." (PMID 34638239, 2021). "It was found that NLRP3 inflammasome could serve as the tumor-promoting effect by the activation of caspase-1 in PCa." (PMID 34930938, 2021). "NLRP3 could also support tumor progression-related phenomena such as EMT, cancer stem cells renewal activation, and an increase in MDCSCs." (PMID 34540671, 2021). "Despite the absence of direct experimental evidence, a potential involvement of IL-33 in ICD contributing to the control of tumor growth could be inferred from the activation of the NLR family pyrin domain containing 3 (NLRP3) in dendritic cells (DCs)." (PMID 34209038, 2021). "In addition to its tumor-intrinsic properties, studies have described a role for NLRP3 in regulating the accumulation of immunosuppressive myeloid-derived suppressor cells (MDSCs) within the tumor microenvironment." (PMID 34638239, 2021). "Still, it is unknown whether NLRP3 activation contributes to tumor de-differentiation via this same impact on the β-catenin signaling pathway in solid tumors." (PMID 34638239, 2021). "Moreover, NLRP3 expression in tumor-infiltrating macrophages has been correlated with the survival, lymph node invasion and metastasis of mammary carcinoma patients." (PMID 34064909, 2021).
tumor (continued). "In addition, recent studies have shown that NLRP3 inflammasome activation within tumor cells can drive resistance to anti-PD-1 checkpoint inhibitor treatment." (PMID 33572196, 2021). "Priming with CpG attenuated Il6 and Nlrp3 expression, further upregulated expression of Nod2, Oas2, RhoA, Pycard, Tlr1/2 and Il12, and enhanced T-cell number and activation while polarizing macrophages to an anti-tumor phenotype." (PMID 33441763, 2021). "CD8+ T-cell activation in response to PD-1 blockade induced a PD-L1/NLRP3 inflammasome signaling cascade that ultimately led to the recruitment of CXCR2+PMN-MDSCs into tumor tissues through HSP70/TLR4/Wnt5a/CXCL5 signaling axis, thereby dampening the resulting antitumor immune response." (PMID 35003065, 2021). "The future development of tumor-specific NLRP3 pathway antagonists may ultimately prove to be the most effective strategy for enhancing the efficacy of checkpoint inhibitor immunotherapies in clinical oncology." (PMID 34638239, 2021). "Additional studies are needed to better understand tumor-specific regulatory mechanisms of NLRP3 to enable the development of tumor-selective pharmacologic strategies capable of augmenting responses to checkpoint inhibitor immunotherapy while minimizing unwanted off-target effects." (PMID 34638239, 2021). "Furthermore, in a xenograft mice model, NLRP3 KO HCC cells delayed tumor development and metastasis as well as increased the sensitivity to NK cell cytotoxicity." (PMID 34502191, 2021). "Indeed, studies have implicated the NLRP3-mediated release of IL-1β in the induction of the IL-22 cytokine by CD4+ T cells, a process observed to support tumor cell proliferation and growth." (PMID 34638239, 2021). "As opposed to a role as an inhibitor of tumor immunosurveillance, there is existing data describing a supportive role of the NLRP3 inflammasome in the development of anti-tumor immune responses, including data illustrating its ability to promote dendritic cell-dependent activation of T cells." (PMID 34638239, 2021). "Interestingly, the long noncoding RNA XLOC_000647 acts as a tumor suppressor and suppresses the progression of PC by downregulating NLRP3." (PMID 34064909, 2021). "Cancer cell-derived extracellular vesicles (EVs) can modify the prostate microenvironment to promote cancer proliferation and can promote the activation of the NLRP3 inflammasome and caspase-1 and IL-1β release, contributing to the maintenance of proinflammatory tumor conditions." (PMID 34064909, 2021). "Increasing attention is focused on identification of the role of the NLRP3 inflammasome in various tumor types, while the role of NLRP3 inflammasome activation in tumor formation, development, and invasion remains controversial depending on types and stages of cancer." (PMID 33534121, 2021). "IL-1β may participate in NLRP3 inflammasome-mediated tumor promotion in the tumor microenvironment since recombinant IL-1β treatment of macrophages increased the migration and invasion of melanoma cancer cells." (PMID 33534121, 2021). "However, few studies have sought to characterize the function and regulation of the NLRP3 inflammasome in tumor cells." (PMID 34638239, 2021). "In the present study, NLRP3/caspase-1/GSDMD pyroptosis pathway was involved in the DDP-induced anti-tumor effect of TNBC in vitro and in vivo, providing evidence that DDP might induce pyroptosis in TNBC." (PMID 34326697, 2021). "Thus, CD8 T cells activate the NLRP3 in antigen-presenting cells (APCs) that promote IL1β maturation and contribute to the induction of antigen-specific anti-tumor immunity amplifying the CD8 effector functions." (PMID 34685542, 2021). "The expressions of NLRP3 in tumor tissues and LLC cells were significantly reduced by HDSB11." (PMID 34239588, 2021).
tumor (continued). "The established inhibitory effects of ketone bodies against the NLRP3 inflammasome may disrupt this anti-tumor mechanism however because this inflammasome has been suggested to influence tumor immunity by mediating tumor-infiltrating lymphocytes." (PMID 34502304, 2021). "Indeed, many of the described pro-tumorigenic properties of NLRP3 have been attributed to its role in driving the expression of IL-1β by tumor-infiltrating myeloid cells." (PMID 34638239, 2021). "In our BC cohort, NLRP3 and PYCARD expression was higher in the tumor samples than in the non-cancerous counterparts, thus confirming inflammasome involvement in establishing a tumor-associated microenvironment to support cancer progression." (PMID 34540671, 2021). "Importantly, a consequence of NLRP3 activation in the tumor are alterations in the systemic host immune response, a concept that is highly relevant in immunotherapeutic approaches targeting inflammatory tumors." (PMID 34531850, 2021). "Western blot data showed that the HDSB11 administration inhibited NLRP3 and cyclin D1 protein expressions compared with the model group in tumor tissues and suppressed NLRP3, procaspase-1, and caspase-1 (p10) expressions compared with the control group in cells." (PMID 34239588, 2021). "Likewise, nuclear localization of NLRP3 was observed in TOX+ CD4+ T cells isolated from tumor lesions." (PMID 34220814, 2021). "In light of its emerging role in regulating anti-tumor immunity, genetic alterations in NLRP3 may predict targeted pharmacologic inhibitors of NLRP3 to augment checkpoint inhibitor immunotherapy." (PMID 34638239, 2021). "Elevated expression of NLRP3 in cells with high expression of IL-4 was observed in the tumor stage." (PMID 34220814, 2021). "Furthermore, the in vivo study demonstrated that BAY-117082 at doses of 2.5 and 5 mg/kg significantly decreased subcutaneous tumor mass, and also reduced NLRP3 inflammasome pathway activation." (PMID 34681768, 2021). "While pyroptosis has been shown to be suppressed in response to NLRP3 activation in certain tumor types, thus promoting tumor cell survival, it is unclear whether the development of this endpoint depends upon the specific stimulus." (PMID 34638239, 2021). "The role of the NLRP3 inflammasome in the tumor microenvironment has been noted." (PMID 33534121, 2021). "The results showed that silencing of NLRP3 obviously slowed down the tumor growth of PCa." (PMID 34930938, 2021). "It has remained unclear what biological processes NLRP3 may regulate in tumor cells and whether these processes may be different from its function in myeloid cell populations." (PMID 34638239, 2021). "In line with this, NLRP3 promotes the mouse lung tumorigenesis induced by benzo(a)pyrene and LPS and favors experimental lung metastasis development by affecting the ability of host NK cells to control the tumor." (PMID 34064909, 2021). "The definitive functions of the NLRP3 inflammasome in mammary malignancy are still unknown, but several studies have demonstrated the pivotal function of IL-1β in tumorigenesis and neoplasm growth." (PMID 34064909, 2021). "NLRP3 activation in both cancer cells and stromal components could result in a cumulative mechanism creating a tumor microenvironment favorable to cancer progression." (PMID 34540671, 2021). "More significantly, our finding revealed that DPP-4i also triggered NF-кB-dependent NLRP3 inflammasome activation, leading to caspase-1-mediated processing of IL-1β and IL-33, two critical proinflammatory cytokines for the tumor-immune-suppressive microenvironment." (PMID 34631556, 2021). "In addition, knockdown of NLRP3 triggered a reduction of NLRP3 and caspase-1 expression levels in excised tumor masses." (PMID 34930938, 2021). "Given the complex nature of the NLRP3 inflammasome and its seemingly contradictory functions in carcinogenesis, future research needs to address important aspects, such as the driving factors in tumor activation and cross-talk pathways." (PMID 35008212, 2021).